HIF1A (hypoxia inducible factor 1 subunit alpha)
Diseases named in the same sentence as HIF1A in open-access papers (continued):
Sharing a sentence is not in itself a finding about the gene and the disease.
osteosarcoma (145 papers, 2008 to 2025). A usually aggressive malignant bone-forming mesenchymal neoplasm, predominantly affecting adolescents and young adults. "HIF1-α is a poor prognostic marker in osteosarcoma, and its downregulation has been associated with increased cell death." (PMID 38534381, 2024). "In osteosarcoma cells, ZnO-NP-induced HIF-1α activation has been linked to autophagy and mitophagy induction and cell death." (PMID 37108134, 2023). "The reduction in SDH then caused the upregulation of HIF1α, thereby rerouting glucose metabolism and aggravating chemoresistance in osteosarcoma cells." (PMID 34763667, 2021). "More importantly, our previous results indicated that TGF-β strengthened the tumorigenesis capability of osteosarcoma cells, and HIF1α has been proven to be associated with tumor stemness regulation." (PMID 34763667, 2021). "Some studies have also shown that HIF-1a is up-regulated in osteosarcoma and is associated with the metastasis and poor prognosis." (PMID 34322597, 2021). "In osteosarcoma, the hypoxia-associated factor HIF-1α inhibited DC functions, which impeded antitumor immunity." (PMID 33816483, 2021). "Although 8-week treatment led to eventual loss of HIF1α(PP) expression, treated osteosarcoma U-2 OS cells acquired tumorigenicity in the subcutaneous tissue." (PMID 25893706, 2015). "Our results indicated that succinate treatment cause a rise in HIF1α in osteosarcoma cells." (PMID 34763667, 2021). "Moreover, the expression of HIF-1α has been correlated to the development of lung metastasis associated with poorer survival in osteosarcoma patients." (PMID 31370265, 2019). "However, the regulatory network associated with HIF-1α in osteosarcoma remains limited." (PMID 38889378, 2024). "The synergistic anti-osteosarcoma activity of Rg3 and doxorubicin was also investigated in vitro and in vivo model of osteosarcoma by regulating mTOR/HIF-1α/VEGF and EMT signaling pathways." (PMID 40507179, 2025). "We propose that RUNX2 and HIF-1α complement each other in osteosarcoma progression through molecular crosstalk." (PMID 40806771, 2025). "Knockout studies of ADCK2 in prostate and osteosarcoma cells have demonstrated a reduced impact of tumor necrosis factor-alpha (TNFα) on hypoxia-inducible factor 1-alpha (HIF-1α), suggesting a potential role for ADCK2 in hypoxia-driven tumor progression." (PMID 40565246, 2025). "cyclin-D1 elevation in control groups can be attributed to HIF-1α which activated the AKT/Cyclin-D1 pathway stimulate the tumor development in osteosarcoma cells." (PMID 40205002, 2025). "Both osteosarcoma (OS) tumours and lung nodules have a hypoxic microenvironment, which induces levels of Hypoxia-Inducible Factors, HIF-1α and HIF-2α within the tumour cells." (PMID 41315643, 2025). "In hypoxic environments, osteosarcoma cells exhibit high levels of HIF-1α and VEGF, which promote angiogenesis." (PMID 40806771, 2025). "For instance, the interaction between KCNJ2 and the HIF1α transcription factor has been shown to establish a positive-feedback loop, contributing to osteosarcoma metastasis." (PMID 38553531, 2024). "Hypoxia plays a pivotal role in promoting the proliferation and metastasis of osteosarcoma through a series of molecular events, which are partially mediated and regulated by HIF-1α." (PMID 38889378, 2024). "Another study showed that Icariside II inhibits glucose metabolism and reduces HIF-1α-induced VEGF expression in human osteosarcoma cells, while simultaneously suppressing angiogenesis." (PMID 39252946, 2024). "Triptolide can also inhibit angiogenesis in osteosarcoma through the HIF-1α, VEGF, and Wnt/β-Catenin pathways." (PMID 39252946, 2024). "The antitumoral effect of ZnO nanoparticles on osteosarcoma has been ascribed to the activation of autophagy and mitophagy due to the stabilization and accumulation of HIF-1α protein by both ROS and Zn2+." (PMID 37108134, 2023).
osteosarcoma (continued). "For initial characterisation of HRE-NanoFIRE, we selected the osteosarcoma derived U2OS cell line as U2OS cells display strong induction of HIF-1α protein in response to hypoxia and robustly activate HRE controlled reporter systems." (PMID 37892227, 2023). "In MG63 osteosarcoma cells, HIF-1α was found to inhibit reactive oxygen species accumulation by directly regulating FoxO1, which interfered with CAT catalase activity, thus resulting in anti-oxidation effects." (PMID 37681913, 2023). "Wang and colleagues elucidated a potential role of SENP1 in osteosarcoma development and invasiveness by the observation that a positive feedback loop exists between HIF-1α and SENP1." (PMID 35465332, 2022). "In osteosarcoma (OS) cells, HIF1A mediates overexpression of the lncRNA FOXD2 adjacent opposite strand RNA 1 (FOXD2-AS1) by binding to the promoter region." (PMID 35659268, 2022). "KRT17 also activates the Akt/mTOR/hypoxia-inducible factor 1α (HIF1α) pathway by promoting proliferation and the Warburg effect, thereby promoting the growth of osteosarcoma cells." (PMID 35281081, 2022). "Previous studies have indicated that YBX1 promotes the translation of HIF1α protein by directly binding to the 5’ UTR of HIF1α mRNA to mediate the metastasis of osteosarcoma." (PMID 35692750, 2022). "A number of studies have analyzed the association of hypoxic markers (HIF-1α, GLUT-1 or Glucose Transporter-1, and VEGF or Vascular Endothelial Growth Factor) with prognosis and clinicopathological characteristics of osteosarcoma." (PMID 35158767, 2022). "Here we report that SphK1 and the S1P1 receptor are involved in HIF-1α accumulation in hypoxic osteosarcoma cells." (PMID 35158767, 2022). "Under hypoxia, lncRNAs act as oncogenic HIF1A targets to promote tumor progression in osteosarcoma cells and bladder tumors." (PMID 35659268, 2022). "The results showed that KRT17 knockout inhibited the proliferation and glycolysis of osteosarcoma cells by inhibiting the Akt/mTOR/HIF1α pathway." (PMID 35281081, 2022). "Overexpression of HIF-1α is a common occurrence in osteosarcoma and has been established as an independent prognostic biomarker." (PMID 34671398, 2021). "We detected the expression of succinate dehydrogenase (SDH), STAT1, and hypoxia-inducible factor 1α (HIF1α) in TGF-β-treated osteosarcoma cells and further tested the effects of these molecules on the cytotoxicity induced by chemotherapeutic agents." (PMID 34763667, 2021). "This is consistent with the reported crucial role of HIF-1α during the migration of human osteosarcoma cells." (PMID 34638942, 2021). "Curcumin has been shown to inhibit hypoxia-induced HIF-1α expression by downregulation of Notch1 expression and acts as a potential anti-cancer agent for the treatment of osteosarcoma." (PMID 34671398, 2021). "Together, these results suggested that TGF-β suppresses SDH activity to upregulate HIF1α, resulting in chemoresistance in osteosarcoma." (PMID 34763667, 2021). "Previous studies have shown that the expression of DEC2 and HIF1α were positively correlated during the progression of human osteosarcoma." (PMID 33990215, 2021). "SENP1 promotes proliferation, invasion, and epithelial–mesenchymal transition of osteosarcoma cells by regulating HIF-1α expression under hypoxia." (PMID 33791211, 2021). "Together, these results suggested that blockade of HIF1α can improve the outcome of chemotherapy, which describes a novel strategy in clinical osteosarcoma treatment." (PMID 34763667, 2021). "A previous study revealed that tetrahydrocurcumin suppressed angiogenesis by targeting HIF-1α and autophagy in human osteosarcoma cells." (PMID 34495871, 2021). "We further found a decrease in SDH expression and an increase in HIF1α expression in TGF-β-treated osteosarcoma cells." (PMID 34763667, 2021).
osteosarcoma (continued). "Here, we demonstrated that HIF1α upregulation resulting from elevated succinate exerted regulatory effects on the glycolytic state and chemotherapy resistance of osteosarcoma cells." (PMID 34763667, 2021). "Sphingosine kinase 1 contributes to doxorubicin resistance and glycolysis of osteosarcoma by advocating HIF-1α expression." (PMID 34540667, 2021). "The previous studies have reported that not only hypoxia but also HIF-1α reciprocally regulates circadian rhythms in human osteosarcoma cells and mouse myoblast cells." (PMID 32316196, 2020). "The commonly upregulated lncRNA MALAT-1 upregulates proangiogenic factors such as VEGF and FGF2 in osteosarcoma by activating the mTOR/HIF-1α signaling pathway as well as via a positive feedback loop of HIF-1α and the lncRNA." (PMID 32992718, 2020). "Increased UCA1 expression by HIF-1α upregulation was also reported in osteosarcoma as well as hypoxic bladder cancer cells through HREs in the UCA1 promoter region." (PMID 32640630, 2020). "In hypoxic conditions, VEGF-A expression is promoted by HIF-1α in U2-OS osteosarcoma cells, and VEGF-A is able to stimulate tumor cell invasiveness." (PMID 32085654, 2020). "Our data revealed HIF-1α was up-regulated in cisplatin resistant osteosarcoma cells, indicating that HIF-1α contributes to cisplatin sensitivity." (PMID 28442599, 2019). "More importantly, HIF-1α can contribute to the proliferation, migration, and chemoresistance in osteosarcoma, chondrosarcoma, and giant cell tumor." (PMID 30782196, 2019). "Increasing evidences have indicated that HIF-1α was not only expressed under normoxia in the osteosarcoma cell line, but also overexpressed in metastatic osteosarcoma tumors." (PMID 30782196, 2019). "Intriguingly, cisplatin resistant osteosarcoma cells display significantly elevated HIF-1α expression under hypoxia." (PMID 28442599, 2019). "To investigate the underlying mechanisms for the miR-199a-modulated cisplatin sensitivity in osteosarcoma cells, we compared the expressions of HIF-1α in SaoS-2 parental and cisplatin resistant cells." (PMID 28442599, 2019). "It is suggested that HMGN5 is an important downstream factor for HIF1A to promote osteosarcoma metastasis." (PMID 31930127, 2019). "For OS, in the subgroup analysis based on histological type, the results showed that HIF-1α overexpression existed poor OS in osteosarcoma (HR = 2.60, 95% CI 2.09–3.24, P < 0.001) and chondrosarcoma (HR = 2.83, 95% CI 1.11–7.22, P = 0.030)." (PMID 30782196, 2019). "There was evidence that hypoxia promoted migration of human osteosarcoma cells by activating the HIF-1α/CXCR4 pathway." (PMID 30782196, 2019). "Exposure of osteosarcoma 143B cells to severe hypoxia (0.5% O2) revealed a strong HIF-1α stabilization." (PMID 29933600, 2018). "Induction of hypoxia was confirmed by stabilisation of HIF-1α protein in all 7 osteosarcoma cell lines." (PMID 29739381, 2018). "In vivo studies with microRNAs or HIF inhibiting drugs have shown that HIF inhibition reduces tumour growth and overcomes chemo-resistance of osteosarcoma; conversely HIF-1α over-expression enhances tumourigenicity." (PMID 29739381, 2018). "In primary osteosarcoma, HIF-1α expression in tumour biopsies is seen to be significantly correlated with metastasis, and in vitro data reveal that VEGF expression driven by HIF-1α is associated with cell migration." (PMID 29098360, 2018). "Overexpression of miR-33b in osteosarcoma cell lines reduces HIF-1α together with cellular proliferation and migration." (PMID 29098360, 2018). "ANGPTL4 was induced by hypoxia in 6 osteosarcoma cell lines, under the control of the HIF-1α transcription factor." (PMID 29739381, 2018). "In osteosarcoma, cell invasion across transwells in vitro is increased under hypoxic conditions reliant upon HIF-1α promoting VEGF-A expression." (PMID 29098360, 2018). "Hypoxia is proven to increase metastasis and progression of osteosarcoma through the HIF-1α/CXCR4 pathway in vitro." (PMID 29661211, 2018).
osteosarcoma (continued). "Our data suggest that the FAK/JNK/HIF-1α signaling pathways have an important role in WISP-1-induced angiogenesis in human osteosarcoma cells." (PMID 28406476, 2017). "The SaOS-2 osteosarcoma cells, transfected with the recombinant plasmid pSilencer2.1-HIF-1α or pSilencer2.1-SCR, were classified as HIF-1α/siRNA group or SCR/siRNA group, respectively." (PMID 28523034, 2017). "In the in vivo and in vitro experimentations, our study demonstrates HIF-1α gene silenced by pSilencer2.1-HIF-1α and corresponding changes of angiogenesis in osteosarcoma." (PMID 28523034, 2017). "In summary, the siRNA-mediated HIF-1α gene silencing in osteosarcoma have successfully amputated the tumor angiogenesis." (PMID 28523034, 2017). "Angiogenesis in osteosarcoma can be inhibited by siRNA-mediated HIF-1α gene silencing, which is expected to provide a novel and attractive target of therapeutic strategies of osteosarcoma." (PMID 28523034, 2017). "Reactive oxygen species (ROS) have been shown to induce HIF-1α as well, although this effect seemed to be time-dependent as external H2O2 induced HIF-1α protein in human osteosarcoma cells at early time points but suppressed it later on." (PMID 26966693, 2016). "In an additional study on osteosarcoma tumors, a significant correlation was observed between increased HIF-1α expression and metastases in patients." (PMID 26393682, 2015). "The role of DEC2 in HIF-1 activation and invasiveness of osteosarcomas was further confirmed by DEC2 knockdown in U2OS-M lowered the fast hypoxic accumulation of HIF-1α and the invasiveness." (PMID 25884381, 2015). "In this study, we demonstrated that HIF-1α positivity predicts an unfavorable prognosis of osteosarcomas." (PMID 25884381, 2015). "In this study, we determined the expression levels of DEC2 and HIF-1α in osteosarcoma samples and analyzed the correlation between DEC2 expression and HIF-1α levels." (PMID 25884381, 2015). "We found that the expression of DEC2 was positively correlated with HIF-1α levels, and HIF-1α expression positively correlated with poor prognosis in osteosarcomas." (PMID 25884381, 2015). "In osteoblast and osteosarcoma cell lines, low HIF-1α expression levels were identified under normoxia which increased when the cells were moved to hypoxic conditions." (PMID 26393682, 2015). "To further explore the role of DEC2 and HIF-1α in osteosarcoma progression, we used the repetitive trans-well approach to select a more invasive subpopulation from the parental U2OS cells." (PMID 25884381, 2015). "Statistical analysis revealed a strong positive correlation between DEC2 and HIF-1α expression in osteosarcomas (Spearman’s rank correlation, ** P < 0.01)." (PMID 25884381, 2015). "In another two studies, the authors indicated that HIF-1α knockdown can markedly reduce the migration ability of esophageal cancer cells and osteosarcoma cells under hypoxia." (PMID 25811359, 2015). "In contrast to other tumors, osteosarcoma shows that DEC2 expression positively correlates with HIF-1α levels, and that high HIF-1α expression levels predict poor prognosis." (PMID 25884381, 2015). "In this study, we investigated the response of osteosarcoma cells to hypoxia and the expression of CXCR4 and HIF-1α in human osteosarcoma specimens and explored the roles of CXCR4 and HIF-1α in the cell migration process." (PMID 24618817, 2014). "In conclusion, this research reports the effect of hypoxia on HIF-1α expression and cell migration and the correlation of HIF-1α with CXCR4 in osteosarcoma cells." (PMID 24618817, 2014). "It was reported that the suppression of HIF-1α activity by trichostatin A downregulates hypoxia-response genes and hypoxia-induced angiogenesis in human osteosarcoma." (PMID 24895555, 2014). "In the literature, the chemosensitivity of pediatric osteosarcomas was also correlated to hypoxic markers, like HIF-1α, as well as Wnt-βcatenin pathway or angiogenesis." (PMID 24216996, 2013).
osteosarcoma (continued). "This screen determined that depletion of ADCK2, PRKAR2B, TRIB2 and TRPM7 most significantly downregulates nuclear accumulation of HIF-1α in response to the treatment of osteosarcoma cells." (PMID 22355351, 2012). "Downstream transcription was HIF-1α-dependent in Ewing's sarcoma, but regulated by both isoforms in osteosarcoma." (PMID 20637078, 2010). "As HIF-1α has already been described to correlate with clinical and survival parameters in osteosarcoma, immunohistochemistry focussed on Ewing's sarcoma." (PMID 20637078, 2010). "HIF-1α protein was stabilised in response to hypoxia in all Ewing's (ES) and osteosarcoma (OS) cell lines tested." (PMID 20637078, 2010). "Nuclear over-expression of HIF-1α has been reported in approximately 60% of clinical osteosarcomas where it correlates with disease grade, stage, recurrence and survival." (PMID 20637078, 2010). "Despite such evidence for hypoxic activation of the HIF transcriptional cascade in osteosarcoma and Ewing's sarcoma cells, little is known regarding the effect of either HIF-1α or HIF-2α on the hypoxic phenotype of these cells." (PMID 20637078, 2010). "For qualifying HIF-1α expression in human osteosarcoma cells (U2OS) using Western analysis, cell lysate was immediately extracted after removal of the hypoxic insert device." (PMID 19727397, 2009). "Therefore, HIF-1α plays a key role in promoting or maintaining the metastatic and invasive behaviours of osteosarcoma cells." (PMID 40806771, 2025). "Additionally, notable changes in the expression of VEGF, E-cadherin, and N-cadherin in osteosarcoma cells have been observed to be correlated with HIF-1α levels." (PMID 40806771, 2025). "However, hypoxia and the presence of HIF-1α downregulate SKA1 expression in osteosarcoma and promote chemoresistance." (PMID 40806771, 2025). "Therefore, HIF-1α promotes the activation of various oncogenes and pathways that promotion of osteosarcoma cells." (PMID 40806771, 2025). "However, hypoxic cells are more vulnerable to radioresistance, and osteosarcoma tumour tissues exhibit elevated HIF-1α expression." (PMID 40806771, 2025). "Therefore, this review focuses on the role of RUNX2 and HIF-1α in the alteration of the tumour microenvironment, which further promotes angiogenesis, metastasis, and resistance to therapy in osteosarcoma." (PMID 40806771, 2025). "Thus, further studies are needed to determine if the degradation of HIF1-α by RACK1 would be exploitable for osteosarcoma therapy." (PMID 38534381, 2024). "However, another study has associated SENP1 overexpression with increased sensitivity to chemotherapy in osteosarcoma, as well as to reduced stemness and HIF-1α down-regulation." (PMID 38534381, 2024). "LINK-A may also act as an upstream activator of HIF1α and participate in the metastasis of osteosarcoma by up-regulating the HIF1α pathway." (PMID 39015175, 2024). "In osteosarcoma (OS) cells under hypoxic conditions, HIF-1α induces the overexpression of the mitochondrial NADH dehydrogenase (ubiquinone) 1 alpha subcomplex 4-like 2 (NDUFA4L2) protein, which in turn promoted OS cell migration, invasion, proliferation, and EMT." (PMID 36701089, 2023). "Finally, since HIF-1α activation has been related also to Doxo resistance in human osteosarcoma cells, we examined if reducing HIF-1α activity would improve Doxo efficacy for BC treatment." (PMID 37407979, 2023). "In osteosarcoma, nucleolin is involved in GSK3β-mediated stability of HIF1α mRNA." (PMID 36359210, 2022). "Knockdown of KRT17 may also decrease the viability and Warburg effect of osteosarcoma cells by significantly affecting the AKT/mTOR/hypoxia-inducible factor 1α (HIF1α) pathway and interrupting the expression of relevant genes." (PMID 36009022, 2022). "Then, the studies in vivo experiments have shown that ZnO NPs could inhibit subcutaneous osteosarcoma proliferation with good biosafety by activating HIF-1α, apoptosis, and autophagy." (PMID 36660426, 2022).